APC (APC regulator of Wnt signaling pathway)
Diseases named in the same sentence as APC in open-access papers (continued):
Sharing a sentence is not in itself a finding about the gene and the disease.
infection (26 papers, 2010 to 2026). The state of being infected such as from the introduction of a foreign agent such as serum, vaccine, antigenic substance or organism. "We found that infection with genotoxin‐producing Salmonella synergises with the loss of APC to enhance genomic instability both in 2D and 3D cultures via activation of the phosphoinositide 3‐kinase (PI3K) pathway." (PMID 31414579, 2019). "Thus, studies involving the APCmin/+ mouse model, the loss of APC heterozygosity induced by environmental factors, such as pathogen infections, can accelerate tumor formation in the gastrointestinal tract." (PMID 41011849, 2025). "A significant increase in activated Yap and β-catenin was observed within the nucleus of E. chaffeensis-infected APC KD cells compared to controls, demonstrating that APC negatively regulates Yap and β-catenin levels in the nucleus during infection." (PMID 38562145, 2024). "We determined that E. chaffeensis TRP120 promotes intracellular infection by ubiquitinating APC for degradation to maintain nuclear Yap and β-catenin levels." (PMID 38562145, 2024). "To demonstrate ubiquitination of APC, we used an enrichment assay to demonstrate that APC is ubiquitinated during early infection when infectious dense core ehrlichiae are present." (PMID 38562145, 2024). "Collectively, these results demonstrate that TRP120 ubiquitinates APC to stabilize active Yap and β-catenin levels in the nucleus to promote infection." (PMID 38562145, 2024). "In this study, we have unveiled a mechanism whereby an Ehrlichia ubiquitinates APC to coordinate with upstream signaling pathway activation to promote infection." (PMID 38562145, 2024). "To determine if APC is a substrate of TRP120 Ub ligase activity we examined APC ubiquitination levels during infection." (PMID 38562145, 2024). "The combination of E. chaffeensis infection with APC knockdown yielded the highest fold change in Yap and β-catenin levels which is likely a result of further reduction of APC over infection alone." (PMID 38562145, 2024). "We determined that APC levels were significantly decreased during infection, despite upregulation of APC transcription, suggesting posttranscriptional regulation of APC, either by translational inhibition or proteasomal degradation." (PMID 38562145, 2024). "If cells expressing MINPP1 are less susceptible to infection, then the fraction of GFP-positive cells that are also APC positive (virus transduced) should be less than the fraction GFP-negative cells that are APC positive." (PMID 32776974, 2020). "MAR1-5A3 was administered 2 or 4 days after WNV infection and APC were examined on days 6 and 9 after infection." (PMID 22144897, 2011). "Since TRP120 is a known HECT E3 Ub ligase, we investigated whether APC is degraded during infection in E. chaffeensis infected THP-1 cells." (PMID 38562145, 2024). "The results demonstrate that TRP120 directly targets APC for ubiquitination during infection." (PMID 38562145, 2024). "However, ubiquitinated APC was undetectable during mid to late infection when Ehrlichia replication is occurring." (PMID 38562145, 2024). "In addition, the quantification of S. Enteritidis in milk samples and serum of infected mice suggest that APC-Cas has potential in food testing and early diagnosis of pathogen infection." (PMID 31937772, 2020). "We have shown previously that increases in cellular/nuclear levels of β-catenin in response to CR infection were neither due to mutational activation of β-catenin or loss of functional APC protein." (PMID 24278135, 2013). "More than likely, other immunological mechanisms of immune regulation (e.g. IL-10, APC dysfunction, in utero tolerization) may play a more prominent role in children (or in more recent infection)." (PMID 21559422, 2011).
infection (continued). "Confocal immunofluorescent micrographs demonstrate temporal degradation of APC and an increase in TRP120 during infection." (PMID 38562145, 2024). "We tried to establish APC-KO cells using colon cell lines, such as FHC, but experienced difficulty because of the extremely poor infection efficiency of the lentivirus; therefore, we established APC-KO HeLa cells." (PMID 35654814, 2022). "Our studies show that the infection of DCs with nrMVA at an optimized MOI results not only in a strong activation of the DCs, but also in a remarkable increased ability to act as APC." (PMID 20628596, 2010). "Regardless, total APC protein levels decrease temporally during infection, with no detectable total APC by 72 hpi, which was demonstrated via confocal microscopy and Western blot." (PMID 38562145, 2024). "Neither the number of mature (SOX10+APC+) nor immature (SOX10+APC−) OLs in the mPFC were affected by infection." (PMID 37596606, 2023). "It was also observed that the percentage of stained BPH-1 (PB450+) and 22Rv1 (APC+) cells do not change the staining efficiency of the respective dyes, after the P/V/F mutant infection." (PMID 35631014, 2022). "APC-annexin V and the 7-AAD stain were used to determine active cell apoptosis via flow cytometry in cFLIP knockdown and SC FHL124 cells to avoid spectrum overlapping with eGFP introduction during lentiviral-based miR30 shRNA infection." (PMID 33837174, 2021). "With insignificant APC activation, it is also no surprise that pro-inflammatory cytokine production is also insignificant at day 7 infection (data not shown)." (PMID 34804036, 2021). "Interestingly, APC protein levels significantly decrease overtime, but APC gene transcription did not, indicating that APC is degraded during infection." (PMID 38562145, 2024). "To assess whether infection had an effect on OL viability and glial activation, we performed immunostaining on brain slices from mice at day 8 p.i. using antibodies specific for OLs (SOX10+), mature OLs (SOX10+APC+), microglia (Iba1+) and astrocytes (GFAP+)." (PMID 37596606, 2023). "Furthermore, immunostaining for PLIN4 revealed it was, albeit not exclusively, co-localized to APC+ mature OLs and that the number of PLIN4-expressing mature OLs in the mPFC was increased by infection." (PMID 37596606, 2023).
colon (24 papers, 2011 to 2025). "We and others have previously demonstrated that STAT3 signaling in response to IL-6 family cytokines provides a rate-limiting signal for gastrointestinal tumors that arise from bona fide oncogenic driver mutations, including in APC, KRAS, or other genes." (PMID 39128004, 2024). "Among the 18 dogs that tested positive for the APC variant in the three families, 15 had current and/or previous histories of GI tumors." (PMID 37505844, 2023). "As expected, most dogs harboring the germline APC variant (15/18 dogs) had a current and/or past history of GI tumors." (PMID 37505844, 2023). "In family 1, the dam with the germline APC variant (dog D) had already given birth to seven litters with 26 offspring between the ages of 1 and 4 years before GI tumors were first detected at 4.6 years, and it transmitted the APC variant to many offspring." (PMID 37505844, 2023). "In particular, using these assays, somatic loss of the wild-type APC allele was successfully detected in the GI tumors of JRTs with heterozygous germline APC variant." (PMID 33461531, 2021). "In fact, only in carriers of APC inactivating mutations MACROD2 had epistasis effects enhancing the growth of gastrointestinal tumors." (PMID 30619475, 2018). "Mutations in the adenomatous polyposis coli (APC) tumor suppressor gene strongly predispose to development of gastro-intestinal tumors." (PMID 21859464, 2011). "It is worth noting that APC is also a frequently mutated gene in digestive system tumors." (PMID 37584393, 2023). "In 2015, a team at the Institute of Biology, Federal University of Pará, Belém, Brazil published a study describing a correlation between APC pathogenic variant and colonic phenotype severity and the occurrence of gastrointestinal tumors among residents in the northern region of Brazil." (PMID 30897307, 2019). "In addition, the WNT ligand expression decrease may be working directly on the canonical WNT/β-catenin signaling, which is strongly associated with colon carcinogenesis though the mutations of APC and β-catenin." (PMID 31835579, 2019). "In this review, we systematically summarized the distribution of APC gene methylation in various GI tumors, and attempted to provide an improved general understanding of DNA methylation in GI tumors." (PMID 33968756, 2021). "Most gastrointestinal tumors were shown to feature APC methylation, while data for duodenal cancer and cholecystic cancer are rare." (PMID 33968756, 2021). "Finally, we elaborated our findings and perspectives on the overall situation of APC gene methylation in GI tumors, aiming to explore the potential research directions and clinical values." (PMID 33968756, 2021). "We hypothesise that Wnt/APC-Myc pathway activation is the initiating event and that the LIN28B-let-7-c-Myc/LIN28B feedback loop accelerates colon carcinogenesis." (PMID 25360631, 2014). "On the other hand, the colon tumors developed in Tg/APC at higher frequency than non-transgenic littermates (hereafter referred to as W/APC)." (PMID 22876303, 2012).
autosomal dominant disease (12 papers, 2014 to 2026). Autosomal dominant form of disease. "FAP is an autosomal dominant inherited disorder caused by a germline mutation in the adenomatous polyposis coli (APC) gene, a tumor suppressor gene, located on the long arm of chromosome 5 (5q21-22)." (PMID 40218169, 2025). "This is an autosomal dominant disease caused by a germline variant in the adenomatous polyposis coli (APC) gene." (PMID 36288164, 2022). "As FPC is a dominant autosomal dominant disease, its major causative gene is the APC gene, which is located at the long arm of chromosome 5, 5q21–22, and the mutation rate of APC in FPC is 30% to 50%." (PMID 29381953, 2017). "FAP is a highly penetrant autosomal dominant disease that results from a germline mutation in the adenomatous polyposis coli (APC) gene located on the chromosome 5." (PMID 27768599, 2016). "APC gene mutation is a cause of the inherited autosomal dominant disease, FAP." (PMID 24959234, 2014). "In a recent study, we demonstrated that JRTs with GI polyps harbor an identical germline variant in the adenomatous polyposis coli (APC) gene, c.[462_463delinsTT] (GenBank ID: LC598892.1) in a heterozygous state; thus, this is an autosomal dominant hereditary disorder (OMIA ID 001916–9615)." (PMID 35717217, 2022). "We recently demonstrated that JRTs with GI neoplastic polyps harbor an identical heterozygous germline variant in the adenomatous polyposis coli (APC) gene, c.[462_463delinsTT] (GenBank ID: LC598892.1), indicating that this is an autosomal dominant hereditary disorder (OMIA ID 001916–9615)." (PMID 36288164, 2022).
genetic disorders (11 papers, 2016 to 2025). "Adenomatous polyposis coli (APC) gene mutations has been linked to the genetic disorder, familial adenomatous polyposis (FAP), in which at least 25% of patients develop desmoid tumors." (PMID 29330550, 2018). "The newfound relationship between the APC/C and chromatin may also play a significant role in tissue specific functions as genetic disorders are beginning to be found from the disruption of the APC/C function." (PMID 34109183, 2021). "The ability to assess chromosome abnormalities based on the analysis of metaphase chromosome spreads can reveal genetic disorders in cells with or without APC-ΔC expression that have survived the treatment with BI6727." (PMID 29549256, 2018).
neurodegenerative disease (6 papers, 2016 to 2024). A disorder of the central nervous system characterized by gradual and progressive loss of neural tissue and neurologic function. "This phenotype partially overlaps with microglial signatures described in neuroinflammation and neurodegenerative diseases and includes genes such as Itgax, Clec7a and genes associated with APC functions, commonly thought of as inflammatory." (PMID 38195627, 2024). "Growing evidence has demonstrated that impaired function of APC/C-Cdh1 and accumulation of its substrates are involved in neurodegenerative diseases." (PMID 29218001, 2017). "Growing evidence suggests that dysregulation of APC/C-Cdh1 is involved in neurodegenerative diseases." (PMID 27514492, 2016). "Interestingly, dysregulation of these processes results in neurodegeneration, linking APC/C-Cdh1 targets to neurodegenerative diseases and particularly to AD." (PMID 36588673, 2022). "Therefore, APC/C-Cdh1 targets are interconnected and involved in neurodegeneration, then representing useful tools to develop new treatments for neurodegenerative diseases." (PMID 36588673, 2022). "Interestingly, growing evidence suggests that dysregulation of APC/C-CDH1 is involved in neurodegenerative diseases, potentially as a consequence of amyloid-β driven proteasome-dependent degradation of CDH1." (PMID 31247897, 2019).
neurological diseases (6 papers, 2015 to 2025). "Furthermore, in an APC mouse mutant model, the DA content is abnormally distributed in different brain regions, and these changes are associated with behavioral and phenotypic changes described in some neurological diseases." (PMID 26495845, 2015). "We recently reported that insulin-dependent inhibition of GSK3β, a kinase with a growing list of neurologic disease links, phosphorylates dynein and regulates its interactions with Ndel1 and APC." (PMID 29404402, 2018). "Understanding the APC/C-Cdh1 signalling pathway in AD might be important to identify new molecular targets for the development of effective disease-modifying treatments for this neurological disorder." (PMID 36588673, 2022).
benign tumors (5 papers, 2003 to 2025). "However, as discussed in detail earlier, Ras mutations can act cooperatively with mutations in other tumour suppressors or oncogenes, for example the tumour suppressors scrib or Adenomatous polyposis coli (APC), to induce the growth of benign tumours." (PMID 36899813, 2023).
haematological disorders (2 papers, 2016 to 2022). "Lack of VDR or APC inactivation can induce haematological disorders." (PMID 27768599, 2016).
mental illness (2 papers, 2015 to 2025). "We identified three studies evaluating a possible association between the APC gene and psychiatric disorders." (PMID 40356044, 2025). "Additionally, current literature suggests co‐occurrent psychiatric disorders are more prevalent in FAP‐patients, possibly associated with the SNP variants in the APC gene." (PMID 40356044, 2025). "This might suggest that the pathogenic variant in the APC gene does not cause a predisposition to developing psychiatric disorders and this increased risk is due to having to live with the disease and its interference with day‐to‐day life." (PMID 40356044, 2025).
neurodevelopmental disorder (2 papers, 2020 to 2025). A behavioral and cognitive disorder with onset during the developmental period that involves impaired or aberrant development of intellectual, motor, or social functions. "Our findings place CTNND2 alongside other WNT-regulating genes such as APC, CHD8, and CTNNB1, whose disruption similarly causes variable neurodevelopmental disorders." (PMID 41502569, 2025).
gastrointestinal disease (1 paper, 2017). A disease that occurs in the gastrointestinal system, excluding the hepatobiliary system. "Taken APC as an example, it was first identified as the cause of the familial adenomatous polyposis syndrome and its dysfunction was closely associated with several gastrointestinal diseases." (PMID 28009985, 2017).
head and neck tumors (1 paper, 2021). "Until now, few studies have reported APC hypermethylation in saliva from HNC patients; however, this epigenetic alteration has been frequently observed in head and neck tumors." (PMID 34206840, 2021).
myopathy (1 paper, 2023). A disease of the muscle in which the muscle fibers do not function properly. "Furthermore, RNA-seq data showed alterations in several genes involved in Wnt signaling, such as APC, DACT1, DKK2, DVL2, and WNT4, emphasizing an important role for Wnt signaling in WB myopathy." (PMID 38130476, 2023).
neoplasms of the nervous system (1 paper, 2025). "First, BDNF, WDPCP, APC and SMO are associated with neoplasms of the nervous system, especially the pituitary gland (group BN)." (PMID 40831500, 2025).
vasculopathy (1 paper, 2020). "Thus, our identified DEGs (RRM2, APC, CHEK1, E2F6, TYMS, E2F7, and CDK6) from the cluster 2 subnetwork are highly related to and consistent with the members of the signaling pathways associated with the immune system, apoptosis, the cell cycle, and vasculopathy." (PMID 32426333, 2020).
APC also shares sentences with these, for which no sentence is quoted: Peutz-Jeghers syndrome (7 papers); Cowden syndrome (6); neuroendocrine carcinoma (4); soft tissue tumors (4); acute lymphoblastic leukemia (3); cervical squamous cell carcinoma (3); cholangiocarcinoma (3); CNS tumors (3); duodenal cancer (3); familial adenomatous polyposis 1 (3); familial breast cancer (3); gallbladder cancer (3); hereditary tumor syndrome (3); lung squamous cell carcinoma (3); skin cancer (3); testicular germ cell tumor (3); type 2 diabetes (3); Adrenocortical tumors (2); anal carcinoma (2); Beckwith-Wiedemann syndrome (2); benign prostatic hyperplasia (2); cardiac disease (2); DICER1 syndrome (2); Duodenal polyposis (2); dyslipidemia (2); endometrioid endometrial adenocarcinoma (2); experimental autoimmune encephalomyelitis (2); familial melanoma (2); Fanconi anemia (2); gynecological cancer (2).
A further 177 diseases each share a sentence with APC in 2 papers or fewer.